E2F1 (E2F transcription factor 1)
Diseases named in the same sentence as E2F1 in open-access papers (continued):
Sharing a sentence is not in itself a finding about the gene and the disease.
cancer (763 papers, 2002 to 2026). A tumor composed of atypical neoplastic, often pleomorphic cells that invade other tissues. "Functionally, we found EXOSC10 overexpression reversed E2F1 deficiency-induced proliferation inhibition, apoptosis enhancement, angiogenesis suppression, and cancer stemness impairment in Huh-7 and Hep3B cells." (PMID 40221814, 2025). "Protein arginine methyltransferase 5 (PRMT5) is over‐expressed in a wide variety of cancers and is implicated as having a key oncogenic role, achieved in part through its control of the master transcription regulator E2F1." (PMID 39021294, 2025). "E2F1 represents a central node interconnected with various signaling pathways implicated in human cancers." (PMID 39119602, 2024). "E2F1 is abnormally expressed in multiple types of cancer, including ccRCC, is directly associated with poor prognosis of cancer, and has been shown to be a key cancer biomarker." (PMID 38890303, 2024). "E2F1 interacts with the retinoblastoma protein (pRB), a key tumor suppressor that is frequently mutated in cancer and with other RB family proteins (RBL1 and RBL2) that modulate its transcriptional activity." (PMID 38344207, 2024). "SET/PP2A axis plays a pivotal role in the colony-formation ability of cancer cells and the stabilization of c-Myc and E2F1 proteins implicated in this process." (PMID 38141761, 2024). "Among these genes, we can find some encoding cancer-relevant transcription factors such as E2F1 CTCF, and ERG and DNA methyltransferase enzymes (DNMT1)." (PMID 38773638, 2024). "Among others, E2f1, E2f3, Kif13a, Rxra, Rxrb, and Rxrg were the most common and prominent genes that emerged in our analysis associated with multiple cancer-related pathways." (PMID 37047531, 2023). "The identified TFs, such as FOXC1, FOXL1, POU2F2, NFIC, NFkB1, MEF2A, GATA2, and E2F1, are mainly associated with different types of cancers and congenital disorders." (PMID 37026010, 2023). "On the other hand, E2F1 possessed a crucial role in mediating multiple cancer hallmark capabilities that regulate metabolism, survival, cell cycle, apoptosis, and metastasis." (PMID 37537694, 2023). "CNVs of E2F1 were reported previously in various type of cancers to be associated with cancer susceptibility." (PMID 36937870, 2023). "To specifically probe the effect of pRb and E2F1 on PVR protein expression, we first transduced cancer cells with a recombinant adenovirus encoding E2F1 (Ad.E2F1)." (PMID 37230983, 2023). "The pooled results indicated that there was a significant association between elevated E2F1 and cancer patients’ poor survival (OS/DFS)." (PMID 37277745, 2023). "We confirmed that in human cancer cells, many of the peptide-encoding lncRNAs represent E2F1-target genes." (PMID 36841868, 2023). "The transcription factor E2F1 plays a crucial role in mediating multiple cancer hallmark capabilities that regulate cell cycle, survival, apoptosis, metabolism, and metastasis." (PMID 37705754, 2023). "As a transcription factor, high E2F1 levels were commonly associated with aggressive cancer and poor patient prognosis for multiple cancer types." (PMID 36292703, 2022). "E2F1 mediates regulation of the cell cycle, and its aberrant activation is strongly associated with poor prognosis in a variety of cancers." (PMID 35371308, 2022). "E2F1, which regulates the transcription of genes encoding proteins involved in DNA repair, DNA replication, mitosis and survival of cancer patients, functions as a key regulator in GC progression." (PMID 35440106, 2022).
cancer (continued). "Following this clue, screening cancer-related genes directly regulated by transcription factor E2F1 was the crucial step to explore the underlying mechanism of malignant phenotypes in RB." (PMID 36096885, 2022). "E2F1 expression was higher in PCa than in benign tissues (benign vs. cancer = 1.18 ± 0.05 vs. 1.64 ± 0.03, p < 0.01), and a high E2F1 expression was associated with higher Gleason scores (GS < 7: 1.44 ± 0.06, GS = 4 + 3: 1.58 ± 0.05, GS > 7: 1.91 ± 0.05)." (PMID 35531101, 2022). "Other studies report that E2F1 also plays an essential role in metabolic reprogramming in cancer cells, causing repressed glucose oxidation in mitochondria and enhanced glycolysis." (PMID 33986804, 2021). "E2F1, often dysregulated and activated in human cancers, is inversely associated with the survival of patients." (PMID 34428336, 2021). "There was a trend that PLANE levels were positively associated with the levels of E2F1 in diverse cancer types in TCGA datasets." (PMID 34145290, 2021). "The abnormal elevation of E2F1 is observed in different types of human cancers and is associated with poor survival prognosis and malignant progress." (PMID 33589572, 2021). "We show that this lncRNA is chromatin-associated and an E2F1 target, and its expression is necessary for cancer cell proliferation." (PMID 31934613, 2020). "The overexpression of E2F1 in cancer cells can be associated with increased resistance to several chemotherapeutic drugs and antimetabolite drugs that target enzymes involved in DNA synthesis." (PMID 33396205, 2020). "Such mutations are frequent in cancer to the extent that the dysregulation of this axis and the resulting continuous activity of E2F1 are described in almost all human malignancies." (PMID 33665206, 2020). "The E2F1/DDX11/EZH2 represents a promising therapeutic target in the clinical management of HCC that is one of the leading causes of cancer-related death globally." (PMID 33614480, 2020). "Further, overexpression of E2F1 concomitant with Rb-loss is implicated in activating a transcriptional program that drives cancer progression, invasion, and metastasis." (PMID 32224870, 2020). "We show that this lncRNA is chromatin-associated and an E2F1 target, and its expression is necessary for cancer cell proliferation and survival." (PMID 31934613, 2020). "These E2F1-related lncRNAs have been reported to play extensive roles in different malignant tumors; however, the underlying mechanisms are poorly understood." (PMID 33054826, 2020). "Our results suggest that PRMT5 and E2F1 are linked through a shared pathway of control that impacts on the migration and invasion of cancer cells." (PMID 32709847, 2020). "E2F-1 has been associated with enhanced chemosensitivity in other cancers due to its activation of Akt." (PMID 31979312, 2020). "Since cell cycle and DNA synthesis proteins are among the main transcriptional targets of E2F1, mutations in the Rb/E2F1 axis allow aberrant cell proliferation preferred by cancer cells." (PMID 33665206, 2020). "Immunostaining of candidate proteins MAX, TCF7L2, YY1, IRF1, STAT6, SP1, and E2F1 (selected based on qPCR results and/or associations to cancer in general) was performed in additional FTC specimens as outlined in the “Materials and Methods” section." (PMID 33063251, 2020).
cancer (continued). "E2F1 knockdown in cancer cells caused cell cycle arrest at the S/G2 phase, leading to DNA gaps and subsequently inhibiting cellular proliferation." (PMID 31534120, 2019). "We found that NBT caused arrest in both G1/S and G2/M synchronized cancer cells by regulating the expression of E2F1 and GADD45α respectively." (PMID 31380287, 2019). "Multiple studies have shown that overexpressed E2F1 is associated with high-grade tumors or metastasis and is observed in many types of human cancer, such as breast, lung, and HCC." (PMID 31598149, 2019). "It is undoubtedly that SMAD4 loss causes the insensitivity of cancer cells to the anti-mitogenic activity of TGFβ, and then abrogating RB-mediated E2F1 suppression." (PMID 31569425, 2019). "We found that NBT exerted anti-proliferative effect on various cancer cells and caused both G1/S and G2/M arrest in synchronized cancer cells through its effects on the expression of E2F1 and GADD45α." (PMID 31380287, 2019). "As a crucial regulator of key events in the metastatic cascade, increased abundancy of E2F1 is associated with aggressiveness and unfavorable prognosis in many cancers such as BC." (PMID 31287003, 2019). "By transcriptional regulation, E2F1 has been implicated in the switch from mitochondrial oxidative phosphorylation to aerobic glycolysis, a crucial metabolic alteration of many cancer cells." (PMID 31627130, 2019). "E2F1 also has defined roles in the replication of many cell cycle-related genes and is highly expressed in cancer cells, and its abundance is strongly associated with poor prognosis in cancers." (PMID 31534120, 2019). "The E2F1/Rb axis is dysregulated in a large proportion of human cancers, but accordingly to the dual activity of E2F1, this represents either a good or a bad prognostic hallmark." (PMID 29048367, 2017). "Considering that different molecular mechanisms can contribute to E2F1 overexpression in cancer, further studies will be needed to confirm that E2F1 somatic mutations within miRNA target site contribute in fact to tumorigenesis." (PMID 28704519, 2017). "Again, multiple cancers are susceptible because E2F-1 regulation of E1A expression is restricted to cells with defective Rb, which is a common mutation in cancers." (PMID 28955655, 2017). "E2F1 is overexpressed in a number of cancers, and its overexpression has been generally associated with a poor prognosis." (PMID 23637916, 2013). "Aberrant cellular proliferation due to deregulation of E2F1 transcriptional activity as a result of either genetic or functional alterations of its upstream components is a hallmark of human cancer." (PMID 22438805, 2012). "WDPMP exome sequencing reveals the first somatic mutation of E2F1, R166H, to be identified in human cancer." (PMID 21955916, 2011).
cancer (continued). "The observed enhancement of drug-sensitive cell proliferation and the involvement of E2F1 in stimulating the growth of this cell population provide valuable insights into potential mechanisms underlying the adaptation of cancer cells to the presence of resistant counterparts." (PMID 38344207, 2024). "YAP1 could regulate multiple genes involved in angiogenesis through E2F1; it also associates with HIF1α in cancer cells under hypoxic conditions, inducing the VEGF-A promoter." (PMID 35937460, 2022). "As a transcription factor with dichotomous functions, E2F1 on one hand transactivates many protein-coding genes involved in cell cycle progression and its high expression causes tumorigenesis, but on the other hand, E2F1 loss has also been demonstrated to induce cancer development and progression." (PMID 34145290, 2021). "Noticeably, the observations showing that E2F1 is implicated in senescence and apoptosis may suggest a dual role of E2F1 in cancer." (PMID 33456565, 2021). "Repressed by the tumor suppressor gene RB1 (retinoblastoma susceptibility gene) in RB-E2F complexes, E2F1 induces cell cycle entry and could be a cancer inducer (Fischer and Müller, 2017)." (PMID 34447748, 2021). "All in all, the understanding of the biological implications of the interaction between PARP1 and E2F1 could serve as the foundation of novel therapeutic avenues for managing cell cycle deregulation, a hallmark of cancer." (PMID 33050515, 2020). "Such hyper-activation of E2F1 could also underlie the significant accumulation of DNA replication stress that represents a barrier to cancer progression if it occurs in the early stages of transformation." (PMID 33665206, 2020). "Therefore, this study focused on the expression of DNA repair-related genes related to E2F1 transcription factor associated with cancer progression." (PMID 33261027, 2020). "C9orf3 may be a novel downstream target of E2F1 associated with cell migration and cancer development." (PMID 31936744, 2020). "Ras-activating mutations could result in E2F1 hyper-activity and trigger DNA replication stress which furthers cancer transformation." (PMID 33665206, 2020). "Some studies suggested that E2F1 is associated with malignant phenotypes in some cancers." (PMID 31897226, 2020). "E2F2, like E2F1, can play a dual role in suppressing and causing cancer." (PMID 33604289, 2020). "Moreover, despite the sequence similarities among the RB family members, only RB preferentially binds to E2F1-4, which explains why uniquely RB mutations are frequently detected in cancers." (PMID 33050515, 2020). "This strongly supports the amplification of E2F1 gene in predisposing to cancer." (PMID 31142321, 2019). "We observed that the genetic inhibition of E2F1 induced loss of viability of these cancer cells." (PMID 29743521, 2018). "Nowadays, more and more studies have linked E2F1 with the metabolic reprogramming in cancer cells." (PMID 30115078, 2018). "Moreover, the anti-proliferative effect of gefitinib has been reported to be associated with suppression of E2F1 expression in several cancer cell lines." (PMID 27655662, 2016). "We found that the lncRNA IQCH-AS1 interacts with E2F1 and miR-15b, suggesting it might be implicated in cancer regulation through the L-FFL network." (PMID 27322142, 2016). "Re-expression of E2F1 caused decreased clonogenicity in HPV-positive cancer cells." (PMID 26670255, 2015).
cancer (continued). "Furthermore, cancer cells with elevated activity of E2F1 have been shown to be highly susceptible to HDAC inhibitor induced cell death and more recently HDAC inhibitors such as SAHA have been shown to suppress the activity of EZH2." (PMID 22629454, 2012). "Integration of the recurrent regions identified by WACE and the gene regulatory network analysis uncovered not only many well-known oncogenes like BIRC5and E2F1, but also a number of novel cancer susceptibility genes such as ECT2, TPX2 and TACC3, which are involved in cell cycle and ECM regulation." (PMID 21806811, 2011). "This could be due to the fact that complete inactivation of E2F1 function may be deleterious to the survival of normal/cancer cells, as E2F1 also regulates proliferation associated genes." (PMID 17407586, 2007). "By delving into the interactions between E2F1 and lncRNAs, researchers may uncover the molecular mechanisms underlying malignant transformation and disease advancement, potentially leading to innovative therapeutic approaches for treating cancer." (PMID 39119602, 2024). "Thus, we may have missed adipocyte-only E2F1-related miRNAs consistent with the cancer-associated E2F1-miRNA network, which we initially anticipated." (PMID 36231008, 2022). "Therefore, NFY activation might contribute to a broad augmentation of gene expression changes, first of all, E2F1 overexpression, associated with cancer progression in GE2-HCC." (PMID 33541355, 2021). "On the other hand, E2F1 also plays an important role in the activation of apoptosis pathways, and the R166H mutation, with its abrogated DNA binding, may contribute to the survival of the cancer cell harboring this mutation." (PMID 21955916, 2011). "Essentially, all cancer cell lines tested possessed distinct E2F1 activity, based on the activation of EREA or ERE73 compared to the corresponding mutant." (PMID 41511373, 2026). "Collectively, these findings confirm that the tumor suppressor E2F targets are specifically activated by distinct E2F1 activity in epithelial cells, from which 90% of cancers arise." (PMID 41511373, 2026). "We have shown that all the cancer cell lines tested exhibit distinct E2F1 activity, whereas this activity is undetectable in normal growing cells." (PMID 41511373, 2026). "The potential utility and limitations are issues to be addressed in utilizing distinct E2F1 activity for cancer specific therapy." (PMID 41511373, 2026). "We showed here that this unique mode of E2F1 regulation of the tumor suppressor genes also applies to epithelial cells, from which 90% of cancers arise." (PMID 41511373, 2026). "The E2F transcription factor 1 (E2F1) regulates the expression of genes involved in different cellular processes in cancer including cell cycle, cell proliferation, apoptosis, and cellular metabolism." (PMID 41540805, 2026). "The findings suggest that distinct E2F1 activity is a widespread and robust marker for the discrimination of cancer cells and highlight its promise for the selective delivery of cytotoxic therapies, minimizing harm to normal proliferating cells." (PMID 41511373, 2026). "Cancer cells survive with concomitant dysfunction of apoptosis-inducing pathways, suggesting the presence of distinct E2F1 activity specifically in cancer cells." (PMID 41511373, 2026). "Functionally, E2F1 deficiency was proved to suppress HCC cell proliferation and angiopoiesis, as well as impaired cancer cell stemness in vitro and in vivo." (PMID 40221814, 2025). "Notably, FOXC1 has been implicated in the regulation of stemness, EMT, and immune evasion, while E2F1 is widely known for its involvement in cell cycle activation and DNA replication, serving as a hallmark regulator of proliferative potential in various cancers." (PMID 40496864, 2025).